BRD4 (bromodomain containing 4)
Diseases named in the same sentence as BRD4 in open-access papers (continued):
Sharing a sentence is not in itself a finding about the gene and the disease.
melanoma (56 papers, 2015 to 2026). A malignant, usually aggressive tumor composed of atypical, neoplastic melanocytes. "In a recent study, a regulatory network dependent on TCF4/BRD4 was linked to the development of resistance to both targeted and immune checkpoint therapies in melanoma." (PMID 38139110, 2023). "A recent study found that Vemurafenib-resistant melanoma was susceptible to BRD4 degradation, and bromodomain inhibitors such as OTX015 and BI-2536 have already had some success in treating carcinomas." (PMID 35560144, 2022). "Our laboratory and others have recently elucidated a role for epigenetic regulators and histone variants in the pathogenesis of melanoma 5, 6 and demonstrated a critical role for the bromodomain (BrD)‐containing protein BRD4 in melanoma maintenance." (PMID 27169980, 2016). "In order to investigate the effect of BRD4 inhibition on gene expression, we performed transcriptional analysis of seven UM cell lines and one cutaneous melanoma cell line with different G protein mutational status." (PMID 26397223, 2015). "This suggests BRD4 may be a drug target specific to RAS-mutant melanoma; indeed, a recent study found that Vemurafenib-resistant melanoma was susceptible to BRD4 degradation." (PMID 35560144, 2022). "Furthermore, high levels of BRD4 are associated with poor outcome in NRASMut melanoma patients." (PMID 29650805, 2018). "Kaplan–Meier survival analysis of 367 melanoma patients with low (n = 342) or high (n = 25) expression of BRD4 revealed that a high level of BRD4 expression is correlated with poor patient prognosis." (PMID 40809945, 2025). "Previously, the authors identified a heterodimer of the alpha and beta chains of hemoglobin in the brain microenvironment that killed brain‐metastasizing melanoma cells by targeting BRD4 and IRS2 proteins." (PMID 40285526, 2025). "Our data suggest that BRD4 binds MITF in melanoma cells and that this interaction is dependent on both SETD6-mediated methylation of BRD4 and MITF acetylation." (PMID 40809945, 2025). "Here, we show that SETD6 binds and methylates BRD4 at K99 in melanoma cells to modulate the genomic distribution of BRD4 and MITF, and that BRD4 binds to MITF in vitro and in cells." (PMID 40809945, 2025). "Consistently, inhibition of AKR1C2 sensitized melanoma cells to ferroptosis and the genetic inhibition of BRD4 enhanced the ferroptosis induced by RSL3 suggesting that BET inhibitors sensitize melanoma cells to ferroptosis." (PMID 41339932, 2025). "The BRD4/IRS2 inhibitor cocktail (designated hereafter as BRIRi) moderated the malignancy of BMMC lines from four different human melanomas." (PMID 40285526, 2025). "Altogether, these findings suggest that SETD6 binds and methylates BRD4 at K99 in melanoma cells to positively regulate cell proliferation and adhesion." (PMID 40809945, 2025). "They conclude that blocking BRD4 via BET inhibitors sensitizes melanoma to GPX4 inhibition-induced ferroptosis and immunotherapy in vivo." (PMID 41339932, 2025). "In melanoma, BRD4 is overexpressed and essential for tumor growth in vivo and interacts with MITF to regulate the expression of genes important for melanin synthesis in melanocytes." (PMID 40809945, 2025). "In melanoma A375and A2058 cells, the complex reduced chromatin binding of BRD4 inthe MYC promoter and inhibited cell proliferation(IC50 to 12.5 μM and 3 μM, respectively)." (PMID 41152016, 2025). "BRD4 regulates the Hippo/YAP signaling, and inhibition of BRD4 with the BET inhibitor NHWD870 represses YAP1 expression via blocking the binding of BRD4 to the YAP1 promoter in melanoma." (PMID 41184230, 2025). "Here, we provide evidence that BRD4 methylation by SETD6 at K99 plays an important role also in melanoma cells." (PMID 40809945, 2025). "Being promising therapeutic targets, we decided to concomitantly deliver PTEN plasmid and BRD4 targeted PROteolysis-TArgeting Chimera (ARV) to drug the “undruggable” c-Myc in BRAFi-resistant melanoma." (PMID 39238805, 2024).
melanoma (continued). "For example, regarding overexpression of bromodomain containing (BRD4) and c-Myc in melanoma and hepatocellular carcinoma, thus, ARV-825, a proteolysis targeting chimera that specifically targets BRD4 and c-Myc was designed for anticancer therapy." (PMID 39179711, 2024). "Cell proliferation assays and clonogenic assays also showed that BRD4 knockout decreased melanoma proliferation." (PMID 38169595, 2024). "While ARV is a BRD4 degrader with potent anticancer effects in BRAFi-resistant melanoma, AL-NANO-treated spheroids showed a gradual decrease in their diameter and area when compared with PL-NANO-treated and control spheroids." (PMID 39238805, 2024). "For this reason, we used the target BRD4 protein degradation strategy to downregulate c-Myc in BRAFi-resistant melanoma." (PMID 39238805, 2024). "BRD2 and BRD4 are overexpressed in human primary and metastatic melanomas, and their inhibition results in downregulation of IL-6 and IL-8." (PMID 36711038, 2023). "Previous studies have reported that BRD2 and BRD4 are overexpressed in melanoma tissues and are essential for tumor maintenance." (PMID 37513949, 2023). "For example, BRD4 is significantly upregulated in melanoma tissues and treatment with BET inhibitors impairs melanoma cell proliferation and metastatic behavior." (PMID 36733715, 2023). "Melanoma with PGC-1α over-expression is characterized by substantial BRD4 protein binding at the PGC-1α gene super-enhancer." (PMID 38135679, 2023). "We further investigated the feasibility of tumor microenvironment–activatable epigenetic BRD4 degradation and validated the potential antitumor efficacy of ENCTACs in a mouse melanoma xenograft model." (PMID 36516252, 2022). "BRD4 is a notorious BET family member that is consistently reported to be amplified or overexpressed in human melanoma lines and primary tumors." (PMID 34575678, 2021). "Previous reports have shown that BRD4 plays a critical role in melanoma, representing a promising therapeutic target." (PMID 33958721, 2021). "There are at least two BET proteins in melanoma, in this case BRD2 and BRD4, that are documented to be overexpressed during melanoma progression." (PMID 34575678, 2021). "JQ1, which targets the BET family of BRD proteins (which includes BRD2, BRD3, and BRD4), effectively inhibited the growth of both the melanoma cell lines even at the lower concentrations." (PMID 34771678, 2021). "Since BRD4 is highly expressed in melanoma, we investigated its requirement in the binding and transactivation of GLI1 promoter by SOX2." (PMID 33958721, 2021). "Altogether, these data indicate that targeting both SMO and BRD4 drastically reduces the ability of melanoma-spheres to self-renew in vitro, supporting their efficacy against melanoma CSCs." (PMID 33958721, 2021). "To investigate the efficacy of the combined blockade of SMO and BRD4 in vivo, we assessed the effects of the drug combination in the growth of orthotopic A375 melanoma xenografts." (PMID 33958721, 2021). "In vitro melanoma cell spread and in vivo tumour development and metastatic representation has been effectively attenuated through Brd4 inhibitor therapy." (PMID 35746919, 2020). "To this end, we first established BRD4 knockout A375 melanoma and A2780 OC cells using the CRISPR/Cas9 system and exposed these cells and the control cells to normoxia (20% O2) or hypoxia (1% O2) to induce HIF1α protein for 24 h." (PMID 32286255, 2020). "BRD4 depletion in A375 melanoma cells using the CRISPR/Cas9 system significantly decreased the expression of c-MYC and suppressed the ability of these cells to form colonies." (PMID 32286255, 2020). "Consistent with the ChIP-seq data showing overlapping peaks in human melanocytes and melanoma cells, we found that both BRD4 and BRD2 were bound to the Tyr and Tyrp1 promoters in Melb-a cells and that (+)JQ1 disrupted binding." (PMID 32151278, 2020).
melanoma (continued). "A previous study demonstrated that BRD4 was commonly overexpressed in melanoma and facilitated recruitment of the transcription elongation factor to drive melanoma progression." (PMID 33052224, 2020). "Overexpression of BRD4 was found in melanoma, and downregulation of BRD4 by genetic knockdown is sufficient to recapitulate the antitumoral effect of BET inhibitors in melanoma cell." (PMID 32175692, 2020). "BET protein consists of BRDT, BRD2, BRD3, and BRD4, among which BRD4 is mainly involved in melanoma progression." (PMID 33052224, 2020). "We show that BET proteins are overexpressed in NRAS‐mutant melanoma and that high levels of the BET family member BRD4 are associated with poor patient survival." (PMID 29650805, 2018). "We found that genetic silencing of BRD4 or pharmacological inhibition of BET/BRD proteins has mainly cytostatic effects in NRAS‐mutant melanoma cells in vitro and minimal effects in vivo." (PMID 29650805, 2018). "Using the TCGA skin cutaneous melanoma dataset and biopsies from 54 patients to search for new targets to treat NRAS‐mutant melanoma, the authors discovered that BRD4 expression was significantly elevated in tumor cells and correlated with poor survival." (PMID 29661909, 2018). "Depletion of BRD4 decreased the viability of NRAS‐mutant melanoma cells, but induced only modest apoptosis." (PMID 29650805, 2018). "We found that the epigenetic regulator BRD4 is expressed at high levels in NRASMut melanoma and that BRD4 is required for tumor cell viability." (PMID 29650805, 2018). "The authors therefore combined BRD4 inhibition with targeting other deregulated signaling molecules in NRAS‐mutant melanoma cells, such as MEK, PI3K, and CDK4/6." (PMID 29661909, 2018). "Following this lead, they tested JQ1, a BET inhibitor and anticancer drug, in NRAS‐mutant melanoma cells and found that it reduces their viability—the degree of reduction correlated with the protein levels of BRD4 reversely." (PMID 29661909, 2018). "In support of this crosstalk, recent studies have shown that loss of members of the Polycomb repressive complex PRC2 amplifies Ras‐driven transcription by triggering an epigenetic switch that sensitizes some tumors, including melanoma, to BRD4 inhibition." (PMID 27169980, 2016). "In our previous study, we found that treatment with the BET inhibitor MS417 impaired melanoma cell proliferation in vitro and tumor growth and metastatic behavior in vivo, effects that were mostly recapitulated by BRD4 silencing." (PMID 27169980, 2016). "BET proteins bind acetylated lysines on histone H3 and H4 and recruit RNA polymerase II to drive transcription and two BET proteins—BRD2 and BRD4 are increased during melanoma progression." (PMID 26426052, 2015). "This led us to investigate whether the newly identified BRD4–MITF interaction in melanoma cells is mediated by the BD of BRD4 and acetylated MITF." (PMID 40809945, 2025). "In view of the finding that the BRD4/IRS2 inhibitor cocktail downregulates the expression of PD‐L1 in melanoma cells, we propose that these inhibitors may represent an additional approach to reduce the expression of PD‐L1 in cancer cells." (PMID 40285526, 2025). "However, here we provide evidence that in melanoma cells the methylation of BRD4 is required for the recruitment of MITF." (PMID 40809945, 2025). "Here, we observed that BRD4 methylation at K99 by SETD6 occurs in melanoma cells." (PMID 40809945, 2025). "To address this hypothesis, we first immunoprecipitated endogenous BRD4 in melanoma cells and confirmed its interaction with endogenous SETD6 at chromatin." (PMID 40809945, 2025). "Next, to test whether BRD4 is a substrate for methylation by SETD6 in melanoma, we used a lysine pan-methyl antibody in control and SETD6 KO cells." (PMID 40809945, 2025).
melanoma (continued). "Importantly, simultaneous delivery of PL-NANO and AL-NANO achieved significant upregulation of PTEN expression levels and degradation of BRD4 protein to ultimately downregulate c-Myc levels in BRAFi-resistant melanoma cells." (PMID 39238805, 2024). "We analyzed BRD4 expression in patients with melanoma before or after trametinib treatment." (PMID 38169595, 2024). "Therefore, treatment with AL-NANO would reduce the levels of oncogenic c-Myc via target BRD4 protein degradation in BRAFi-resistant melanoma." (PMID 39238805, 2024). "In addition, BRD4 promotes the progression of melanoma by regulating the expression of secreted phosphoprotein 1 (SPP1) through the nuclear factor-kappa B2 (NF-κB2) pathway." (PMID 38229152, 2024). "Together, these results suggest that YAP1 is a main downstream effector of BRD4 in melanoma." (PMID 38169595, 2024). "Furthermore, the change in BRD4 expression (BRD4post-BRD4prior) was positively correlated with the poor prognosis of patients with melanoma treated with trametinib." (PMID 38169595, 2024). "In melanoma, BRD4 directly interacts with the enhancer of SPINK6 and mediates its expression." (PMID 37369946, 2023). "This combinatorial treatment synergizes in inducing signs of DNA damage in melanoma cells, consistently with the role of BRD4 in promoting DNA repair, and with previous studies pointing to the induction of DNA damage following pharmacological inhibition of the HH/GLI signaling." (PMID 33958721, 2021). "The isobologram summarizes the combination index (CI) at the IC50 when the SMO inhibitor MRT-92 and the BRD4-degrader MZ1 were combined, showing a moderate synergistic anti-proliferative effect (CI < 1) in melanoma cells independently of their BRAF, NRAS, and NF1 mutational status." (PMID 33958721, 2021). "BET protein involvement in melanomagenesis was demonstrated by Segura at al. when it was shown that BRD2 and BRD4 are overexpressed in human melanoma cell lines and tissues, controlling the expression of certain genes involved in cell cycle progressions and survival." (PMID 34575678, 2021). "Furthermore, BRD4 inhibition was shown to reduce the interaction between BRD4 and CDK9 at the MYC locus and prevented the increase in MYC expression caused by i-CDK9 in HeLa, lung cancer, and melanoma cells." (PMID 34207158, 2021). "Moreover, bromodomain-containing 4 (BRD4) was rapidly recruited to the PD-L1 locus, accompanied by increased H3K27ac and RNA Polymerase II (RNA Pol II) occupancy in melanoma cells after IFNγ stimulation." (PMID 34365463, 2021). "This suggests that MITF and BRD4 are also likely to interact in melanocytes and melanoma cells." (PMID 32151278, 2020). "Importantly, the same concept proved successful in mutant NRAS-driven malignant melanoma, where BRD4 and MEK inhibitors synergized to inhibit tumor growth in mouse melanoma models." (PMID 32046099, 2020). "Mechanistically, BET inhibitors suppressed melanoma progression via the BRD4/NFKB2/SPP1 axis." (PMID 33052224, 2020). "Indeed, analysis of the TCGA cutaneous melanoma dataset revealed that BRD4 and TCF19 were positively associated in melanoma and that the levels of TCF19 inversely correlated with patient's survival (P = 8.3 × 10−3)." (PMID 29650805, 2018). "To determine the effect of BRD4 blockade, we silenced BRD4 in NRAS‐mutant melanoma cells." (PMID 29650805, 2018). "Our studies have uncovered BRD4 as a key vulnerability in NRAS‐mutant melanoma and establish that co‐targeting BET and MEK may be an effective strategy that could be rapidly translated for the treatment of melanoma refractory to current therapies." (PMID 29650805, 2018). "Therefore, we identified a novel combinatorial therapeutic strategy by targeting loss of phosphatase and tensin homolog deleted on chromosome 10 (PTEN) tumor suppressor gene and upregulated BRD4 oncoprotein as Myc-dependent vulnerabilities of drug-resistant melanoma." (PMID 39238805, 2024).
melanoma (continued). "Thus, we tested whether combined inhibition of SMO and blockade of BRD4 may synergize in reducing self-renewal ability of melanoma CSCs." (PMID 33958721, 2021). "The bromodomain and extra terminal domain (BET) family, including BRD2, BRD3, BRD4, and BRDT, is a key epigenetic regulatory factor, which is overexpressed in melanoma cells, regulating DNA replication and cell cycle progression." (PMID 41492362, 2026). "Mechanistic studies revealed that this co-formulation upregulated PTEN levels, degraded BRD4, and ultimately downregulated c-Myc to curb the proliferation of BRAF inhibitor (BRAFi)-resistant melanoma cells." (PMID 40284496, 2025). "Specifically, they noted that the overexpression of BRD4, a member of BET family, upregulated a metabolic enzyme, called Aldo-Keto Reductase family 1 member C2 (AKR1C2), in melanoma cells." (PMID 41339932, 2025). "To explore the potential of BRD4, GAB2, and IRS2 as therapeutic targets for melanoma brain metastasis, we evaluated the anti‐melanoma functions of small‐molecule inhibitors of these proteins." (PMID 40285526, 2025). "Mechanistically, we uncover a novel chromatin-localized interaction between BRD4 and MITF in melanoma." (PMID 40809945, 2025). "This chromatin complex plays a pivotal role in selective recruitment of BRD4 and MITF to different genomic loci in melanoma cells." (PMID 40809945, 2025). "In this study, ARV-825 (ARV) was selected as specific BRD4-targeted PROTAC to achieve target degradation and downregulation of BRD4 protein following subsequent suppression of c-Myc levels in VEM-resistant melanoma." (PMID 39238805, 2024). "Inhibition of BRD4 using BET inhibitors suppressed YAP1 expression and led to blunted melanoma growth when combined with treatment with the MEK inhibitor trametinib." (PMID 38169595, 2024). "This is the very first report illustrating concomitant delivery of a lethal combination of BRD4 PROTAC and a tumor suppressor gene to cooperatively inhibit the progression of drug-resistant melanoma." (PMID 39238805, 2024). "Treatment with the BRD4 inhibitor JQ1 or BAY 1238097 blocks BRD4 binding to the super-enhancer and PGC-1α expression, suppresses melanoma cell proliferation in vitro, and inhibits tumor growth in a mouse model." (PMID 38135679, 2023). "Mechanistically, BET inhibitors sensitize melanoma cells to sunitinib by inhibiting the BRD4/GDF15 axis and BRD4/IL6/STAT3/GDF15 axis." (PMID 36720918, 2023). "To further elucidate the specific protein that mediates BET inhibitor-induced sensitization of melanoma cells to sunitinib, we overlapped the downregulated differentially expressed genes after BET inhibitor treatment and after BRD4 silencing." (PMID 36720918, 2023). "The silencing of BRD2 and BRD4, as well as treatment with BET inhibitors (BETis), can hinder the growth of melanoma." (PMID 37513949, 2023). "Mechanistically, BET inhibitors sensitize melanoma cells to sunitinib by inhibiting the BRD4/GDF15 axis and the BRD4/IL6/STAT3/GDF15 axis." (PMID 36720918, 2023). "Of note, BRD4 inhibitor NHWD-870 strongly reduced the invasion and metastasis of melanoma both in vivo and in vitro." (PMID 37369946, 2023). "To investigate the cellular uptake of ARV@PDSA and achieving proteolysis of BRD4, we first labeled PDSA nanoparticles with Nile Red and tested them in human cervical cancer cells (HeLa) and murine melanoma cells (B16F10)." (PMID 37066758, 2023). "Here we show that co-targeting BRD4 and SMO elicits a significant antitumor activity in melanoma, including a drastic reduction of 2D and 3D melanoma cell growth and melanoma stem cell-like self-renewal." (PMID 33958721, 2021). "Gene expression and IHC analysis of human tissue biopsies have confirmed higher levels of BRD2 and BRD4 in primary and metastatic tumors relative to melanocytes and nevi, suggesting that these BET proteins are involved in melanoma tumorigenesis." (PMID 34575678, 2021).